COX4I2 (cytochrome c oxidase subunit 4I2)
Description:
Component of the cytochrome c oxidase, the last enzyme in the mitochondrial electron transport chain which drives oxidative phosphorylation. The respiratory chain contains 3 multisubunit complexes succinate dehydrogenase (complex II, CII), ubiquinol-cytochrome c oxidoreductase (cytochrome b-c1 complex, complex III, CIII) and cytochrome c oxidase (complex IV, CIV), that cooperate to transfer electrons derived from NADH and succinate to molecular oxygen, creating an electrochemical gradient over the inner membrane that drives transmembrane transport and the ATP synthase. Cytochrome c oxidase is the component of the respiratory chain that catalyzes the reduction of oxygen to water. Electrons originating from reduced cytochrome c in the intermembrane space (IMS) are transferred via the dinuclear copper A center (CU(A)) of subunit 2 and heme A of subunit 1 to the active site in subunit 1, a binuclear center (BNC) formed by heme A3 and copper B (CU(B)). The BNC reduces molecular oxygen to 2 water molecules using 4 electrons from cytochrome c in the IMS and 4 protons from the mitochondrial matrix.
Synonyms: COX4L2; COXIV-2; COX4B; dJ857M17.2; COX4-2; COX4
Tractability: Antibody: UniProt predicts a signal peptide or a membrane-spanning region.
Gene: Protein-coding gene on chromosome 20 (31,637,875 to 31,645,027, forward strand). Ensembl gene ENSG00000131055.
Subcellular location: Mitochondrion inner membrane
Pathways (Reactome):
Metabolism: Complex IV assembly; Respiratory electron transport
Cellular responses to stimuli: Cytoprotection by HMOX1
Gene Ontology:
Biological process: mitochondrial electron transport, cytochrome c to oxygen; cellular respiration; generation of precursor metabolites and energy; oxidative phosphorylation
Cellular component: mitochondrion; mitochondrial inner membrane; mitochondrial intermembrane space; respiratory chain complex IV; mitochondrial membrane
Genetic constraint (gnomAD): Loss-of-function variants: 17 observed, 23.64 expected, observed/expected ratio (o/e) 0.72, 90% interval 0.49 to 1.08. The upper end of that interval is the gene's LOEUF score, 1.08, which puts it in group 4 of 6, group 1 being the genes least tolerant of losing a copy. Missense variants: 224 observed, 233.47 expected, observed/expected ratio (o/e) 0.96, 90% interval 0.86 to 1.07. Synonymous variants: 80 observed, 82.2 expected, observed/expected ratio (o/e) 0.97, 90% interval 0.81 to 1.17.
Gene-disease validity (ClinGen):
ClinGen rates the evidence that COX4I2 causes each of these diseases.
mitochondrial disease (autosomal recessive): Limited.
Homologues: Orthologues: chimpanzee COX4I2 (98% identical), macaque COX4I2 (92% identical), dog COX4I2 (81% identical), rabbit COX4I2 (80% identical), pig COX4I2 (79% identical), guinea pig COX4I2 (76% identical), mouse Cox4i2 (74% identical), rat Cox4i2 (71% identical), zebrafish cox4i2 (46% identical), tropical clawed frog cox4i2 (42% identical), Drosophila melanogaster COX4 (34% identical), Drosophila melanogaster COX4L (27% identical), and 1 more. Paralogues in human: COX4I1 (51% identical).
Diseases named in the same sentence as COX4I2 in open-access papers:
COX4I2 is named in the same sentence as 22 diseases in open-access papers, as found by Europe PMC text mining. Sharing a sentence is not in itself a finding about the gene and the disease. The quoted sentences say what the papers report.
glioma (4 papers, 2015 to 2022). A benign or malignant brain and spinal cord tumor that arises from glial cells (astrocytes, oligodendrocytes, ependymal cells). "In contrast, the isoform switch from COX4i2 to COX4i1 in glioma cells was associated with increased COX activity and respiration." (PMID 32075102, 2020).
colorectal cancer (2 papers, 2022 to 2025). A primary or metastatic malignant neoplasm that affects the colon or rectum. "We investigated the potential oncogenic role of COX subunit 4 isoform 2 gene (COX4I2) in colorectal cancer (CRC) by least absolute shrinkage and selection operator (LASSO) and COX regression analysis to examine whether COX4I2 overexpression can predict colorectal cancer (CRC) prognosis." (PMID 36064310, 2022).
pheochromocytoma (2 papers, 2022 to 2025). "Our previous work found COX4I2 was associated with angiogenesis in pheochromocytoma." (PMID 36172142, 2022). "Fibroblasts mediate the angiogenesis of pheochromocytoma by increasing COX4I2 expression, possibly by affecting ANG1 and HGF." (PMID 36172142, 2022). "Single-cell RNA sequencing technology provides great convenience for understanding the expression and location of COX4I2 in cells of different subtypes in pheochromocytoma tissue." (PMID 36172142, 2022). "The purpose of this study was to explore the role of COX4I2 in regulating angiogenesis in pheochromocytoma." (PMID 36172142, 2022). "In conclusion, fibroblasts mediate the angiogenesis of pheochromocytoma by increasing COX4I2 expression, possibly by affecting ANG1 and HGF." (PMID 36172142, 2022). "Using proteomics detection and analysis, it was found that the differential protein COX4I2 was significantly up-regulated in the pheochromocytoma samples of the rich blood supply group, while the differential protein in the poor blood supply group was PLAT." (PMID 36172142, 2022). "By comparing with the expression profile of COX4I2, we can better observe its accurate localization in pheochromocytoma." (PMID 36172142, 2022). "Distribution of COX4I2 was evaluated by scRNA-seq in one case of pheochromocytoma and the findings were verified by immunostaining." (PMID 36172142, 2022). "The purpose of this study is to explore the accurate localization and expression of COX4I2 in pheochromocytoma tissue and to preliminarily verify whether it plays an exact role in angiogenesis in tumor microenvironment." (PMID 36172142, 2022). "This important discovery provides us with a clearer direction to study the involvement of COX4I2 in pheochromocytoma angiogenesis, allowing our research team to pay more attention to the tumor microenvironment rather than the tumor cells themselves in subsequent studies." (PMID 36172142, 2022). "Furthermore, we found that the protein level of COX4I2 was positively correlated with the microvessel density in pheochromocytoma." (PMID 36172142, 2022). "Our study firstly showed that COX4I2 is not localized in pheochromocytoma tumor cells, but in fibroblasts in the tumor microenvironment." (PMID 36172142, 2022). "Immunostaining of COX4I2, CgA and α-SMA were performed in the same area of pheochromocytoma tissue." (PMID 36172142, 2022). "By interfering with COX4I2 mRNA in fibroblasts, we observed a decrease in the expression of ANG1 and HGF, which suggests that COX4I2 may act as an upstream gene of ANG1 and HGF to mediate a pathway of pheochromocytoma angiogenesis." (PMID 36172142, 2022).
adrenal pheochromocytoma (1 paper, 2024). "COX4I2 is highly correlated with the blood supply of adrenal pheochromocytoma and contributes to angiogenesis." (PMID 38409358, 2024).
Alzheimer disease (1 paper, 2023). A progressive, neurodegenerative disease characterized by loss of function and death of nerve cells in several areas of the brain leading to loss of cognitive function such as memory and language. "Briefly considering common disease themes between Alzheimer’s disease and the ALS-Ox subtype, expression of oxidation-associated transcripts COX4I2, NDUFA4L2, and OXR1 is consistent with reported literature, although CP is known to be upregulated in Alzheimer’s55." (PMID 36609402, 2023).
Bell's palsy (1 paper, 2021). Partial or complete paralysis of the facial muscles of one side of a person's face. "The results of this study show the mechanism underlying the effect of Cox4i2 on nerve injury caused by HHV7 infection, and support the application of cell therapy, gene therapy, or additional fundamental biological approaches in treating Bell’s palsy in the future." (PMID 34026834, 2021).
bone tumors (1 paper, 2025). "Clinically, these findings have dual implications: firstly, COX4I2 may serve as a prognostic biomarker for patients with bone tumors; secondly, targeting COX4I2 or its exosomal packaging and delivery pathways could potentially enhance the efficacy of ferroptosis-based therapies." (PMID 40977891, 2025).
diabetes (1 paper, 2024). "Therefore, while the enhanced functions of ATP5F1B and COX4I2 support cellular metabolism under normal conditions, in the pathological state of diabetes and especially DKA, they might intensify metabolic stress and cellular stress responses." (PMID 39469619, 2024).
neuroblastoma (1 paper, 2025). Neuroblastoma (NB) is the most common solid, extracranial childhood tumor. "In addition, analysis of the 498SEQC dataset showed that RGS5, NDUFA4L2, and COX4I2 are all significantly correlated with EPAS1 expression in neuroblastoma." (PMID 41118218, 2025).
osteosarcoma (1 paper, 2025). A usually aggressive malignant bone-forming mesenchymal neoplasm, predominantly affecting adolescents and young adults. "To further validate the cellular origin of COX4I2 within the tumor microenvironment, we examined its expression across annotated cell populations using single-cell RNA sequencing data derived from osteosarcoma samples." (PMID 40977891, 2025). "In our investigation, we established that COX4I2 was actively transferred from CAFs to osteosarcoma cells via exosomes, reducing intracellular Fe2+ and ROS levels, thereby suppressing ferroptosis, and promoting tumor proliferation." (PMID 40977891, 2025). "We provided evidence that COX4I2 derived from CAFs exosomes functioned as an onco-protein, inhibiting ferroptosis in osteosarcoma cells and promoting tumor proliferation both in vitro and in vivo." (PMID 40977891, 2025). "The exosomal transfer of COX4I2 protein from CAFs to 143B osteosarcoma cells was evaluated by Western blot, confocal microscopy, and transmission electron microscopy." (PMID 40977891, 2025). "Collectively, these findings elucidated a novel regulatory axis involving CAFs, exosomal COX4I2, and ferroptosis, offering a promising therapeutic target for disrupting stromal support mechanisms in osteosarcoma." (PMID 40977891, 2025). "Analysis of CAF and exosomal COX4I2 in clinical osteosarcoma samples would be critical for translational relevance." (PMID 40977891, 2025). "Mechanistic investigations demonstrated that the COX4I2 protein was transferred from CAFs to osteosarcoma cells via exosomes, leading to reduced Fe2+, ROS accumulation, MDA level, and preserved mitochondrial morphology, and enhanced tumor cell proliferation." (PMID 40977891, 2025). "This represents the first report identifying COX4I2 as a key regulator of stromal-mediated ferroptosis evasion in osteosarcoma, thereby enhancing our understanding of mitochondrial signaling within the tumor microenvironment." (PMID 40977891, 2025). "Collectively, these results elucidate a novel CAFs exosomal COX4I2/ferroptosis axis that contributed to osteosarcoma progression, providing valuable insights into stromal regulation and potential therapeutic targets." (PMID 40977891, 2025). "The Cox analysis results of TARGET database, GSE16091, and GSE21257 revealed that patients with high COX4I2 expression exhibited significantly shorter survival time compared to those with low COX4I2 expression in osteosarcoma." (PMID 40977891, 2025). "Together, these findings were consistent with the results of experiments in vitro, demonstrating compelling evidence for exosomal COX4I2 protein’s role in promoting osteosarcoma malignant proliferation through ferroptosis inhibition." (PMID 40977891, 2025). "Functional experiments demonstrated that exosome-mediated delivery of COX4I2 suppressed ferroptosis in osteosarcoma cells and enhancd cell proliferation and mitochondrial integrity." (PMID 40977891, 2025). "Further investigations demonstrated that CAFs transfer COX4I2 to osteosarcoma cells through exosomes and suppressed ferroptosis by reducing intracellular Fe2+ levels and ROS accumulation, thereby promoting tumor proliferation." (PMID 40977891, 2025). "In conclusion, this study demonstrates that CAFs exosomal COX4I2 serves as a pivotal regulator of osteosarcoma progression by inhibiting ferroptosis." (PMID 40977891, 2025). "This suggested that CAFs may induce malignant characteristics in osteosarcoma by the interactation between tumor cells with osteosarcoma cells through the transmission of COX4I2 protein by mediating ferroposis." (PMID 40977891, 2025). "Collectively, these results underscore the significance of COX4I2-mediated suppression of ferroptosis in osteosarcoma progression and suggest that disrupting this axis may offer innovative treatment strategies." (PMID 40977891, 2025).
pulmonary hypertension (1 paper, 2022). Increased pressure within the pulmonary circulation due to lung or heart disorder. "In the Human Lung Cell Atlas project, lung pericytes are identified using COX4I2, TBX5, and KCNK3 and its potential implication in pulmonary hypertension is proposed." (PMID 35722109, 2022).
tumor (11 papers, 2017 to 2025). "Emerging evidence have implicated COX4I2 in angiogenesis and tumor progression (Li JP." (PMID 40977891, 2025). "Studies in vivo further revealed that overexpression of exosomal COX4I2 markedly promoted tumor growth while inhibiting ferroptosis." (PMID 40977891, 2025). "IHC staining confirmed that the COX4I2 protein was significantly upregulated in tumor tissues from the overexpression group compared to those in the control group." (PMID 40977891, 2025). "To quantify this observation, we compared COX4I2 expression levels across tumor cells and CAFs using violin plots." (PMID 40977891, 2025). "Here, we demonstrated a novel molecular pathway whereby activation of COX4I2 significantly induces fibroblast growth factor 1 (FGF1) expression and thus promotes tumor-associated angiogenesis and the activation of cancer-associated fibroblasts (CAFs)." (PMID 36064310, 2022). "The data extracted from GSE37182 and GSE10950 indicated that there was a significant difference between COX19 and COX4I2 expression in tumor tissues and controls (P < 0.05)." (PMID 36064310, 2022). "However, the action of COX4I2, which is upregulated under hypoxic conditions, in tumor progression is poorly understood." (PMID 36064310, 2022). "Although its role in tumour cells has not been confirmed, COX4-i2 can increase the production of ROS in hypoxic carotid body spherical cells, suggesting that COX4i2 may play the same function in tumour cells." (PMID 32928258, 2020). "Notably, COX4I2 expression was significantly elevated in CAFs compared to tumor cells (P < 0.001)." (PMID 40977891, 2025). "Furthermore, our findings demonstrated that the inhibition of exosome release, through GW4869, could effectively counteract the tumor-promoting effects mediated by COX4I2 transfer." (PMID 40977891, 2025). "This methodology facilitated the identification of COX4I2 as a hub gene highly enriched in CAFs rather than in tumor cells." (PMID 40977891, 2025). "Through the identification of a novel stromal–tumor communication axis, we offer profound insights into the non-cell-autonomous regulation of ferroptosis and highlight COX4I2 as a potential prognostic biomarker and therapeutic target." (PMID 40977891, 2025). "Here, we sought to determine whether an increase in extracellular succinate levels is able to induce HIF2α protein accumulation in physiological oxygen tensions and increase expression of ADORA2A, COX4I2 and NDUFA4L2 in the context of a tumor background." (PMID 35740651, 2022). "In addition, how tumor cells adapt to hypoxia through COX in the tumor microenvironment is an interesting and significant topic, and our subsequent work will focus on these two aspects to try to elucidate the exact pro-cancer mechanism of COX4I2." (PMID 36064310, 2022). "The scRNA-seq revealed high mRNA expression of COX4I2 in fibroblasts rather than tumor cells." (PMID 36172142, 2022).
cancer (6 papers, 2021 to 2025). A tumor composed of atypical neoplastic, often pleomorphic cells that invade other tissues. "We identified COX4I2 as a stromal hub gene, highly enriched in cancer-associated fibroblasts (CAFs)." (PMID 40977891, 2025). "We therefore performed a LASSO-COX regression based on TCGA-COAD data and identified COX4I2 as well as COX19 in respiratory chain complexes as potential cancer risk factors." (PMID 36064310, 2022). "Migration assays confirmed that COX4I2 overexpression increased CAF recruitment by the cancer cells." (PMID 36064310, 2022). "We hypothesize that COX4I2 may be a downstream factor of hypoxia-triggered signaling cascades involved in the onset of cancer proliferation." (PMID 36064310, 2022). "Additionally, COX4I2 may be associated with fibroblast growth factor 1 (FGF-1), which plays pivotal roles in EMT, cancer-associated fibroblast activation, and angiogenesis." (PMID 39457539, 2024). "Whereas the precise functions of NDUFA3, NDUFA13 (also called GRIM19), COX7A1, COX4I2 and ATP5F1D in oxidative phosphorylation remain somewhat poorly understood, increased expression of NDUFA4L2 is known to drive pro-oncogenic phenotypes in numerous cancer types." (PMID 34782604, 2021).
neurodegenerative disease (2 papers, 2021 to 2022). A disorder of the central nervous system characterized by gradual and progressive loss of neural tissue and neurologic function. "Here, we found that the species of Mn can increase or arrest the expression of genes such as MT-CO1, MT-CYB, MT-ND4, and COX4I2, which are associated with glycolysis and glycogenesis, and oxidative phosphorylation, along with neurodegenerative diseases such as AD, HD, and PD." (PMID 34941782, 2021).
adenocarcinoma (1 paper, 2025). A common cancer characterized by the presence of malignant glandular cells. "Other studies support our data showing mitochondrial energy metabolism gene expression varies between the metaplasia to adenocarcinoma disease sequence with some genes decreasing (ATP12A, COX4I2) and others increasing (COX8C)." (PMID 40381373, 2025).
COX4I2 also shares sentences with these, for which no sentence is quoted: glioblastoma (2 papers); osteoarthritis (2); asthma (1); Obesity (1); pancreatic insufficiency-anemia-hyperostosis syndrome (1); prion disease (1); respiratory diseases (1).